NGF (nerve growth factor)
Diseases named in the same sentence as NGF in open-access papers (continued):
Sharing a sentence is not in itself a finding about the gene and the disease.
leukemia (8 papers, 2014 to 2025). A malignant (clonal) hematologic disorder, involving hematopoietic stem cells and characterized by the presence of primitive or atypical myeloid or lymphoid cells in the bone marrow and the blood. "Transduction efficiency (>90%) of donors cells was confirmed by expression of a truncated nerve growth factor (NGFR) protein co-expressed by the bi-cistronic retroviral vectors encoding ICN1 and leukemia was monitored in the blood of animals by flow cytometry." (PMID 40319015, 2025). "This is consistent with other studies indicating that circulating NGF levels and NGF gene expression in immune cells are influenced by immunologically related disorders (human inflammatory disease and leukemia)." (PMID 40427122, 2025). "Transcription corepressor CTBP2 has been reported to directly bind acinus, which is regulated by NGF (nerve growth factor), inhibiting its stimulatory effect on cyclin A1 expression in leukemia." (PMID 25628645, 2014). "While it is uncertain what provides these AML1–ETO-expressing leukemia cells a growth advantage, one hypothesis is their crosstalk with bone marrow stromal cells that express nerve growth factor (NGF)." (PMID 31551508, 2019). "NGF provoked initial activation by enhanced expression and fast degradation of TrkA whereas Gambogic Amide showed a more sustained TrkA activation pattern with a constantly increasing expression over three days in a human leukemia cell line." (PMID 31465471, 2019). "NGF binds to its cognate receptor, TrkA, and may therefore drive leukemia." (PMID 31551508, 2019). "However, the branches of the ATM pathway, ILK signaling, NGF, PPAR and VEGF pathways were regulated oppositely in the adult and pediatric leukemia samples." (PMID 27870639, 2016). "This study also confirms the observation that in the absence of other cytokines, some leukemia cells can survive in the presence of NGF, introducing the concept that under certain circumstances TRKA inhibition may be beneficial." (PMID 30046390, 2018).
mood disorder (8 papers, 2018 to 2023). A cognitive disorder a disturbance in which the person's mood is hypothesized to be the main underlying feature. "Identification of the NTRK1 mutation linked with bipolar disorder sheds light on the new role of NGF-TrkA signaling and its relevance to mood disorders." (PMID 33235206, 2020). "Many neurotrophins are associated with the pathogenesis of mood disorders, such as the nerve growth factor (NGF) and brain-derived neurotrophic factor (BDNF)." (PMID 31231295, 2019). "Thus, it seems that NGF has an important role in the pathophysiology of mood disorders, but with aging this association can be attenuated." (PMID 30767081, 2019). "Numerous studies reported reduced BDNF and NGF levels in patients with mood disorders." (PMID 28550529, 2018). "However, the peripheral increase in growth factors (BDNF and NGF) and inflammatory cytokines initiated by nerve damage may be involved in the pathophysiology of mood disorders as they are related to pain." (PMID 34589875, 2020). "Interestingly, in another study after 8 weeks of intensive administration of antidepressants, significant improvement in the clinical symptoms of mood disorders was demonstrated without changes in NGF level." (PMID 30767081, 2019).
spinal cord injury (8 papers, 2014 to 2023). Penetrating and non-penetrating injuries to the spinal cord resulting from traumatic external forces (e.g., WOUNDS, GUNSHOT; WHIPLASH INJURIES; etc.). "It has been suggested that upregulation of GAL expression in DRG neurons in micturition pathways after spinal cord injury (SCI) may be mediated by changing neurotrophic factors expression such as NGF and brain-derived neurotrophic factor (BDNF)." (PMID 34948196, 2021). "Interestingly, increased levels of BDNF, NGF, and NT-3 in the injured spinal cord may be the main therapeutic effect of using hUCB-MSCs to treat spinal cord injuries (SCI)." (PMID 37185735, 2023).
synovitis (8 papers, 2009 to 2025). Inflammation of a synovial membrane. "Contribution of the NGF-TrkA pathway to pain behaviour and joint pathology is also evident in models of OA where administration of AR786 reduced the pain and synovitis associated with OA." (PMID 27145816, 2016). "Neurotrophins and especially NGF are expressed in the synovial fluid and tissue of patients with peripheral synovitis." (PMID 19490633, 2009). "Animal studies have assessed several treatments for synovitis that are designed to interfere with specific biological molecules, such as anti-tumor necrosis factor agents, anti-nerve growth factor antibodies, and antiproteases (anti-matrix metalloproteinases and anti-ADMATS)." (PMID 36443725, 2022). "Injection of NGF into rat knees induces pain behavior and synovitis." (PMID 27145816, 2016). "Synovitis and inflammatory mediators such as PGE2 and nerve growth factor (NGF), sensitize nociceptors and heighten pain perception." (PMID 40717911, 2025). "Presence of synovitis was positively correlated with NGF area fraction (r= 0.78, p= 0.03), but not with radiological severity (r= –0.09, p= 0.38) or Safranin-O area fraction (r= –0.26, p= 0.28)." (PMID 35300334, 2022). "We recently demonstrated that subchondral pathology is associated with knee OA pain independent of chondropathy and synovitis and that increased nerve growth factor (NGF) expression at the osteochondral junction and increased osteoclast density are key features associated with bone pain in knee OA." (PMID 39176036, 2024). "Analogous to human knee OA, NGF expression was not correlated with OA severity or synovitis grade." (PMID 35300334, 2022).
Ventricular arrhythmia (8 papers, 2013 to 2025). "NGF released from ischemic cardiac tissue plays a pivotal role in sympathetic nerve sprouting, which may cause life-threatening ventricular arrhythmias." (PMID 23843937, 2013). "Our data show that infarcted hearts exposed to a PPI, but not an H2 receptor blocker, had decreased myocardial Mg2+ content, increased NGF expression, and consequently increased ventricular arrhythmias, probably through a superoxide-dependent pathway." (PMID 30153299, 2018).
Atrophy (7 papers, 2011 to 2025). Any weakening or degeneration, especially through lack of use. "High NGF levels are maintained throughout life, with reduced NGF levels resulting in cholinergic and sympathetic neuronal atrophy." (PMID 32033187, 2020). "Reduced NGF expression has been previously shown to result in cholinergic and sympathetic neuronal atrophy." (PMID 32033187, 2020). "For example, i.c.v. injection of NGF reverses cholinergic neuron atrophy and improves the learning abilities of aged rats with impaired spatial memory." (PMID 24801530, 2014). "We decided to classify atrophy rates based on the well-established clinical cutoff of the 10th percentile, and described the findings instead of performing statistical testing in the small NGF cohort." (PMID 32375872, 2020). "Animal studies suggest that NGF may reverse, or slow down the progression of Alzheimer's related cholinergic basal forebrain atrophy." (PMID 21541365, 2011). "For instance, the NB and medial septum neurons fully depend on NGF for their trophism, and therefore impairment of its retrograde transport from the cortex to the basal forebrain or its conversion from pro-NGF could induce cholinergic atrophy." (PMID 36203811, 2022). "Moreover, emerging concepts from Chen and Mobley (2019) introduced the “signalling endosome hypothesis,” which posits that deficits in NGF-containing endosome transport, rather than NGF itself, precipitate neuronal atrophy." (PMID 40656325, 2025).
Autoimmunity (7 papers, 2016 to 2025). The occurrence of an immune reaction against the organism's own cells or tissues. "SORCS3 is associated with both autoimmunity and tumors, but the specific pathway regulating SLE pathogenesis, perhaps NGF/p75NTR or other pathways, needs to be further explored." (PMID 37554401, 2023). "Many studies suggest that DPN is associated with abnormal metabolic pathways, microvascular disease, nerve growth factor, autoimmunity, inflammation and oxidative stress." (PMID 35042559, 2022). "In the attempt to clarify the role of the NGF system in autoimmunity, the animal model of MS, the EAE model, has been employed, but due to limit number of such studies, the results are quite controversial." (PMID 31996225, 2020). "In this way, NGF acts protectively in the context of protective autoimmunity, where the body develops mechanisms to cope with CNS damage by restricting and controlling the degeneration and/or promoting the regeneration." (PMID 31996225, 2020). "To date, although the pathogenesis of DPN remains unclear, previous studies suggest that DPN is associated with oxidative stress, microvascular disease, abnormal metabolic pathways, nerve growth factor, autoimmunity, and inflammation." (PMID 35643885, 2023). "Several hypotheses have been proposed for factors contributing to the etiology of IC/BPS, including epithelial dysfunction, neurogenic inflammation, mast cell upregulation, autoimmunity and infection, growth factors (e.g., NGF, VEGF, PD-EFGF) and genetics." (PMID 29706873, 2018). "The customizability of these receptors could enable them to sense morphogen gradients established by proteins such as NGF and the BMP family during embryonic development, or to report on the local immune state in the context of cancer, autoimmunity and infectious disease." (PMID 39542025, 2025).
bipolar disorder (7 papers, 2008 to 2024). A disorder of the brain that causes unusual shifts in mood, energy, activity levels and the ability to carry out day-to-day tasks. "Meanwhile, the reductions of plasma levels of BDNF and NGF have been shown in bipolar disorder, and manic and depressed patients." (PMID 38473763, 2024). "Meanwhile, the reduction of plasma levels of BDNF and NGF has been shown in bipolar disorder and manic and depressed patients." (PMID 38473763, 2024). "The NGF, FGF2, NT-3, BDNF, IL-1-β, and dopamine factors also indirectly impact the action of GSK-3β in bipolar disorder." (PMID 37569304, 2023). "Factors such as fibroblast growth factor (FGF)-2, vascular endothelial growth factor (VEGF), nerve growth factor (NGF), and insulin-like growth factor (IGF)-1 might be potential candidate biomarkers for bipolar disorder." (PMID 31118905, 2019). "Gene NGF has a nonzero loading in the first PC for bipolar disorder." (PMID 31530853, 2019).
head and neck squamous cell carcinoma (7 papers, 2018 to 2025). A squamous cell carcinoma that arises from any of the following anatomic sites: lip and oral cavity, nasal cavity, paranasal sinuses, pharynx, larynx, and salivary glands. "In head and neck squamous cell carcinoma, the NGF–TrkA axis...; anticipated on-target effects of NGF/TrkA inhibition include sensory paresthesias/hypoalgesia, mitigated by dose titration, intermittent scheduling, local-field delivery when feasible, and rescue with non-opioid analgesic algorithms." (PMID 41445745, 2025). "It is reported that in head and neck squamous cell carcinoma (HNSCC) cells, the NGF/TrkA axis confers resistance to the EGFR inhibitor Erlotinib through the EMT process." (PMID 34568317, 2021).
Infertility (7 papers, 2017 to 2024). "In the present study, we evaluated the involvement of NGF in the human male reproductive system by analysing the expression of NGF and both its receptors (TrkA and p75NTR) in semen and sperm from fertile men and men with infertility caused by varicocele or urogenital infections (UGIs)." (PMID 38137566, 2023). "Furthermore, lower levels of NGF or IGF-1 in seminal plasma are associated with infertility." (PMID 38792459, 2024). "In the seminal plasma, the NGF protein concentration and TrKA mRNA expression appear to be different in fertile and infertile men." (PMID 38792459, 2024). "The available data indicate that NGF, EPO, and IGF-1 positively influence sperm motility, and lower levels of NGF or IGF-1 in seminal plasma are associated with infertility." (PMID 38792459, 2024). "Recently, the expression of NGF and its receptors were evaluated in semen and sperm from fertile men and patients with infertility." (PMID 38792459, 2024). "As expected, fertile men showed better sperm parameters as well as lower levels of NGF, F2-IsoPs, and IL-1β compared with men with infertility." (PMID 38137566, 2023). "In this paper, we evaluated the role of NGF and its receptors in the sperm, testis and epididymis of fertile men and men with infertility due to varicocele or a UGI." (PMID 38137566, 2023). "Further evidence includes lower NGF levels in infertile individuals." (PMID 39595370, 2024). "Indeed, it has been demonstrated that NGF has an improving effect on male infertility in aging mice and is able to restore fertility in male mice with busulfan-induced infertility." (PMID 36361912, 2022). "It means that pharmaceutical interventions targeting NGF may provide a possible novel therapeutic strategy for treating adenomyosis-related infertility." (PMID 32676925, 2021). "Notably, neurotrophins, brain-derived neurotrophic factor (BDNF), and nerve growth factor (NGF) in follicular fluid of women have been used for different infertility diagnoses." (PMID 34604101, 2021). "The search was conducted using combinations of keywords related to “NGF”, “EPO”, “IGF-1”, “male reproductive system”, “sperm, “sperm motility”, “sperm vitality”, “infertility”, and “ART”." (PMID 38792459, 2024). "Our findings suggest that the role of seminal NGF cannot be simply considered positive or negative because it is largely affected by the reproductive condition of men (e.g., fertile or infertile with different pathologies)." (PMID 38137566, 2023).
leprosy (7 papers, 2012 to 2025). Leprosy is a chronic infectious disease affecting primarily the skin and peripheral nervous system. "The authors suggest decreased levels of NGF as a relevant factor in nervous involvement, such as the loss of sensitivity characteristic of leprosy." (PMID 41156731, 2025). "this research aimed to analyze nerve growth factor (NGF) contents as diagnostic tools for early disability in leprosy patients and the cut-off point value." (PMID 33425178, 2020). "In lepromatous forms of leprosy, higher mean expression levels of NGF and its receptor are associated with larger and more diffuse lesion patterns and greater nerve involvement." (PMID 29867937, 2018). "We discuss the involvement of NGF in the induction of neural damage and the pathophysiology of pain associated with peripheral neuropathy in leprosy." (PMID 29867937, 2018). "This review demonstrates that, within lesions associated with leprosy, NGF and TGF-β respond to inflammatory processes and tissue damage while triggering tissue remodeling." (PMID 29867937, 2018). "Therefore, this research aimed to analyze the validity of NGF concentration as a diagnostic tool for early deformities in leprosy patients and to determine its cut-off point." (PMID 33425178, 2020). "Thus, NGF could play an important role in the prevention of ulcerations resulting from nociception loss, as observed in leprosy and other peripheral neuropathies." (PMID 29867937, 2018). "Studies indicate NGF, as well as the presence of its direct autoantibody (anti-NGF), as possible indicators of neural damage in leprosy according to its expression." (PMID 41156731, 2025). "Another study also detected lower expression of NGF in leprosy patients compared to healthy individuals." (PMID 41156731, 2025). "The present study discovered that NGF concentrations in the blood plasma of MB type leprosy patients with disability grades 0 and 1 were significantly different (p = 0.0000)." (PMID 33425178, 2020). "In contrast, the decrease in endogenous levels of NGF and the TrKA receptor was demonstrated directly in skin lesions of leprosy patients and correlated with nociceptive changes." (PMID 32696914, 2020). "ROC curve analysis was conducted to determine the limit value of NGF concentration for leprosy with disability grade 0 and grade 1." (PMID 33425178, 2020). "Multiple neurotrophin-related signaling pathways are involved in nerve damage and repair and the role of neurotrophins in leprosy have already been approached, mainly regarding two neurotrophins, NGF and BDNF." (PMID 32696914, 2020). "For this reason, we have not been able to compare the findings of other researchers in determining the threshold value of serum NGF in leprosy patients." (PMID 33425178, 2020). "This means that there were significant differences in blood plasma NGF levels between MB leprosy patients with grade 0 and grade 1 disability." (PMID 33425178, 2020). "This research suggests that NGF can be used as a detection marker for early disability in leprosy, with the cut-off value of 81.43 pg/mL." (PMID 33425178, 2020). "Further supporting a relationship between NGF and leprosy, Scully and Otten and others by previous studies reported the involvement of NGF in sympathetic and sensory neuron apoptosis." (PMID 29867937, 2018). "The presence of NGF is generally more apparent in patients with the highest probability of nerve damage (i.e., those with lepromatous leprosy and young patients)." (PMID 29867937, 2018). "The present review describes the role of NGF in the pathogenesis of leprosy and its correlations with different clinical forms of the disease and with the phenomena of regeneration and neural injury observed during infection." (PMID 29867937, 2018). "Understanding how Nerve Growth Factor (NGF) is regulated in leprosy and HIV-leprosy co-infection may contribute to immunomodulatory treatments and neuroimmune response control." (PMID 41156731, 2025).